INSR (insulin receptor)
Diseases named in the same sentence as INSR in open-access papers (continued):
Sharing a sentence is not in itself a finding about the gene and the disease.
cancer (continued). "IGF-1 secreted by activated PSCs and CAFs via sonic hedgehog pathway activates IGF-1R in cancer cells triggering phosphorylation of insulin-receptor or Src substrates to promote PDAC metastasis via intracellular pathways such as RAS/MAPK." (PMID 32660466, 2020). "The insulin receptor (IR)/PI3K/AKT/mTORC1 pathway is the most commonly dysregulated pathway in human cancers and plays a crucial role in stimulating tumor cell metabolism, growth, proliferation, and motility." (PMID 32252811, 2020). "Recently, PGRMC1 has been reported to interact with the insulin receptor (IR), and contributes to glucose uptake in cancer cells." (PMID 32887925, 2020). "It is thought that INSR is related to increased cell proliferation and metastatic potential 34, while Serpin A5 has been found to play dual roles in cancer, inhibiting the growth of tumors but promoting tumor metastasis." (PMID 32863958, 2020). "For example, metabolic “waste” produced by cancer cells activates systemic inflammatory responses, which can interfere with hepatic insulin receptor signaling and glucose homeostasis." (PMID 32193527, 2020). "First, reduced blood insulin concentrations at the cancer cell membrane results in less binding to the insulin receptor with resulting downstream inhibition of the PI3K-Akt-mTOR (PAM) signaling cascade, as well as the RAS-RAF-MEK-ERK pathway." (PMID 33270630, 2020). "Results showed that the “zinc finger protein 106,” which is involved in the insulin receptor signalling pathway, was the main activated upstream in cancer (p value = 2.9E − 06, z-score = 2.0)." (PMID 31827511, 2019). "The current study describes the overexpression of INSR, which is mainly INSR-A, in the vasculature in a variety of human cancer types, where it is observed to predict decreased patient survival." (PMID 30559346, 2019). "A receptor processing defect in IGF-1R and INSR was observed in LoVo cells, a cancer cell line reported to lack expression of the proprotein convertase furin, although no obvious decreases in the occupancy of N-glycans was noted in these cells." (PMID 31101650, 2019). "This knowledge would be instrumental for the assessment of the relevance of INSR and the application of INSR targeting for angiostatic cancer therapy." (PMID 30559346, 2019). "While the insulin signaling pathway has been classically associated with metabolic types of action, evidence accumulated over the past several years identified the INSR as an important player in cancer development." (PMID 31771180, 2019). "Activation of insulin receptor (INSR) in cancer cells triggers the signaling cascades of phosphatidylinositol 3-kinase (PI3K)-AKT pathway, which promotes proliferation and glycolysis but inhibits apoptosis." (PMID 31315616, 2019). "In this study, we demonstrate that the insulin receptor (INSR) is one of these tumour EC markers having a clear role in tumour angiogenesis and a potential impact for the clinical management of cancer therapy." (PMID 30559346, 2019). "Hyperinsulinaemia promotes cancer cell proliferation by stimulating the insulin receptor directly and insulin-like growth factor-1 indirectly." (PMID 30027404, 2018). "In the outlier control samples, we identified proteins DNMT1 (DNA Methyltransferase 1), INSR (insulin receptor) and HDAC1 (histone deacetylase 1) displaying a regulation pattern previously associated with different cancer types, including MIBC." (PMID 30419021, 2018). "Metabolic reprogramming in cancer encompasses the insulin receptor (IR) as a player of energy homeostasis and proliferation." (PMID 30680065, 2018). "Of the different insulin receptor isoforms the A isoform, which has predominant mitogenic activity, is often overexpressed in cancer cells, providing a selective growth advantage to malignant cells when exposed to insulin." (PMID 29238337, 2017).
cancer (continued). "We evaluated the role of IGF2 signaling pathway in MRT cell proliferations, and also confirmed this hormone promotes cancer cell growth through stimulation of IGF1R and INSR, which is associated with activation of PI3K/AKT and RAS/ERK pathways." (PMID 28521298, 2017). "We found several cellular growths or cancer-related pathways that were associated with SNPs of NRG1, VAV3, DIRC3, SEPT11 and INSR." (PMID 28703219, 2017). "Circulating insulin and IGF-1 primarily converge with intrinsic cancer cell metabolic processes via binding to their cell surface receptors, specifically insulin receptor (IR) and IGF-1R." (PMID 28959684, 2017). "Increased levels of insulin receptor have been reported in cancer cells and insulin-like growth factor (IGF) signaling was shown to play a role in HPV-infected lesions and tumorigenesis." (PMID 27537218, 2016). "The insulin receptor substrates, as major mediators of downstream pathways involved in cell proliferation and survival, are important proteins for cancer pathogenesis." (PMID 26755644, 2016). "Studies performed in vitro showed that activation of the insulin receptor (IR) or insulin‐like growth factor‐1 receptor augments proliferation and inhibits apoptosis of cancer cells." (PMID 26843513, 2016). "Further elucidation of the role of BAIAP2L1 in context of the insulin receptor signaling pathways of cancer cells is warranted for developing cancer therapeutics by targeting cancer-specific metabolism." (PMID 26222696, 2015). "How the two isoforms of INSR differentially activate the mitogenic versus the metabolic signaling pathways in cells is under active investigation, especially as many cancer cells overexpress INSR-A." (PMID 26720346, 2015). "The insulin-like growth factor 1 receptor (IGF1R) and the insulin receptor (IR) are receptor tyrosine kinases that are expressed in cancer cells." (PMID 25699021, 2015). "The insulin receptor substrate-1 (IRS-1), previously known as a major docking protein for both the type 1 insulin-like growth factor receptor and the insulin receptor in cancer cell growth and proliferation signaling, was also a validated target of miR-145-5p." (PMID 25888956, 2015). "Beyond its well-known role in glucose homeostasis, INSR stimulates cell proliferation and migration and is often aberrantly expressed in cancer cells." (PMID 25679508, 2015). "Again, non-cancerous cells responded to changes in IGF1R and INSRs levels conversely to cancer cells: IGF1R/INSRA overexpression caused decreased migration and invasion, while IGF1R/INSR downregulation was associated with enhanced migration and invasion." (PMID 24809298, 2014). "Elevated levels of insulin and INSR have been reported in several human cancers, including breast, colon, and lung, suggesting the existence of a common etiological link." (PMID 24434591, 2014). "It is important to define the role of INSR in cellular response to stress with regards to development of drug resistance in cancer." (PMID 24885964, 2014). "We now extended our study and investigated the impact of IGF1R and INSR level modulations on colony formation ability, an additional cancer-promoting feature." (PMID 24809298, 2014). "IRS1 has been shown to be involved in cancer progression and metastasis by mediating proliferative and anti-apoptotic functions of the INSR and IGF1R signaling." (PMID 23818951, 2013). "For example, cancer and the ErbB signaling pathway, insulin receptor regulation, and axon guidance pathways are preserved between mouse and human viral targets." (PMID 23369080, 2013). "There has been a steady increase in the interest in the importance of insulin and the insulin receptor in cancer progression." (PMID 23983688, 2013). "The insulin receptor is highly expressed in adipose, muscle, and kidney tissues, while it is overexpressed in breast and prostate cancer cells as well as in most normal and neoplastic haematopoietic cells." (PMID 24073332, 2013).
cancer (continued). "Compensation for AKT inhibition through InsR/IGF-IR signaling has therapeutic implications in cancer." (PMID 23844554, 2013). "It is now recognised that the insulin receptor is expressed by many malignant tumours including those of prostate, lung, thyroid, colon, and breast." (PMID 23983688, 2013). "The major insulin receptor isoform expressed on cancer cells is the A isoform which has a higher affinity for insulin than the B isoform and is more readily activated by circulating insulin." (PMID 23983688, 2013). "In different cancers types, insulin receptor isoform composition or insulin receptor substrate (IRS) isoforms are different to healthy tissue." (PMID 23251408, 2012). "FGFR1 and INSR are both known to be involved in carcinogenesis and thus become novel, attractive targets for cancer therapeutic strategies." (PMID 21211025, 2011). "Studies have demonstrated that MTFs, such as human epidermal growth factor receptor (HER), fibroblast growth factor receptor (FGFR), β-catenin, Notch, insulin-like growth factor 1 receptor (IGF-1R), and insulin receptor (IR), play critical roles in tumorigenesis and cancer progression." (PMID 39404930, 2024). "NAMPT and INSR are potential therapeutic targets in multiple cancer types and may be crucial in suppressing CSCs." (PMID 39107908, 2024). "The oncogenic role of the insulin receptor (IR) has been observed in diverse cancer types." (PMID 38443798, 2024). "The insulin receptor (IR) plays a crucial role in cancer biology." (PMID 39410536, 2024). "The oncogenic effect of insulin could be due to the overexpression of insulin receptor by cancer cells, but also to its ability to interact with the IGF1 receptor, especially at supraphysiologic doses and with the use of long-acting analogues." (PMID 38146457, 2023). "However, the alternatively spliced insulin receptor found in fetal tissue and cancer cells has a higher affinity for proinsulin." (PMID 36830626, 2023). "Moreover, this tridepside improved the insulin-stimulated glucose uptake through the insulin receptor (IR)/IRS/Akt/GLUT2 pathway in the human liver HepG2 cancer cell line." (PMID 36675938, 2023). "This interactive network was associated with metabolic diseases, peptide hormone metabolism, NODAL signaling, regulation of beta-cell development, WNT ligand biogenesis and trafficking, antimicrobial peptides, PI3K/AKT signaling in cancer, and signaling by the insulin receptor." (PMID 37340445, 2023). "Other genes include immune responses of T cells in cancer cells, insulin-receptor-related protein (INSRR), MHC II complex HLA-DQB and HLA-DQA, IL-12A, IL-20, glucose transporter 4 (GLUT4), insulinoma-associated protein 1 (INSM1), and insulin receptor (INSR)." (PMID 36769056, 2023). "Indeed, both in vitro and in vivo studies demonstrated that insulin and insulin receptor (IR) played a key role in cancer biology." (PMID 35222270, 2022). "Clinical and laboratory data argue that targeting Type I IGF receptor (IGF1R) alone may be insufficient to disrupt this pathway as the insulin receptor (IR) may also be a relevant cancer target." (PMID 33429867, 2021). "IGF1R and INSR genes are direct targets of BRD4 in several cancer models." (PMID 34440844, 2021). "Finally, the role of nuclear InsR/IGF1R in cancer biology is of exceptional translational relevance." (PMID 33918477, 2021). "InsR was expressed in cancer cells as well as in cancer vasculature." (PMID 34202040, 2021).
cancer (continued). "Visfatin is shown to significantly promote malignant progression of this cancer via activation of the insulin receptor (IR) and the phosphoinositide 3-kinase (PI3K)/AKT and mitogen-activated protein kinase (MAPK)/extracellular signal-regulated kinase (ERK) signaling pathways." (PMID 33799622, 2021). "INSR overexpression is regarded as a common feature of many types of cancer." (PMID 32637033, 2020). "However, the malignant cell biological response to insulin cannot be predicted only on the basis of the insulin receptor content, as a malignant cell is complex and other factors are activated to promote cancer growth." (PMID 32156062, 2020). "Insulin receptor overexpression is a common event in human cancer." (PMID 32033443, 2020). "Besides, activation of insulin receptor or insulin-like growth factor receptors has a key role in cancer cell resistance to anoikis." (PMID 31579438, 2019). "As a functional role for insulin/INSR in cancer has been suggested and markers of the tumour endothelium may be attractive therapeutic targets, we investigated the role of INSR in angiogenesis." (PMID 30559346, 2019). "IGF-1R and INSR are homologous members of the receptor tyrosine kinase superfamily of transmembrane glycoproteins, are widely expressed in normal tissues, and are expressed at high levels in malignant tumors." (PMID 31101650, 2019). "However, there are multiple lines of evidence to suggest that cancers can use the INSR/IGF1R pathway as a resistance mechanism to other treatments and that IGF1R inhibition can augment responses to standard chemo‐ and radiotherapy." (PMID 31179642, 2019). "This might indicate that the drug targets of AEW541, namely receptors IGF1R and Insulin receptor, are connected to a vulnerable area within the metabolic pathways active during the development of both cancer types." (PMID 31208363, 2019). "Indeed, as part of the current focus of pharmacological research on the INSR/IGF1R pathway in the treatment of cancer, more than 100 clinical trials have already investigated INSR/IGF1R inhibition." (PMID 28882129, 2017). "Notably, in cancer cells, IR is often predominantly expressed as the “fetal” insulin receptor isoform A (IR-A), which binds both insulin and IGF-II." (PMID 28275367, 2017). "Secondly, hyperinsulinemia may also be a potential link between type 2 diabetes and cancer, as insulin is not only a metabolic hormone but also a growth factor that has anti-apoptotic and mitogenic effects via activation of the insulin receptor." (PMID 29238337, 2017). "Within the IGF network not only the IGF1R but also the INSR exerts cancer-promoting functions." (PMID 24809298, 2014). "Most cancers express both the insulin receptor and the IGF1R genes." (PMID 25114970, 2014). "INSR and IGFRs have likewise been well characterized on the cell membranes of these cancers." (PMID 24885964, 2014). "The insulin receptor activating signaling pathways is capable of stimulating cancer cell proliferation, protection from apoptotic stimuli, invasion and metastasis; it also stimulates normal cells like vascular smooth muscle cell proliferation and migration needed for cancer growth." (PMID 23431471, 2013). "A third factor is represented by insulin receptor (IR) overexpression by most cancers." (PMID 24115945, 2013). "In essence, the impact of insulin on cancer risk may be large because of its capacity to deliver a more mitogenic, IGF-like signal either through isoform A of the insulin receptor or through insulin receptor: type I IGF receptor hybrids." (PMID 23983688, 2013). "The ability of the insulin receptor to form hybrids with type I IGF receptor may contribute to the effects of insulin on cancer progression." (PMID 23983688, 2013).
cancer (continued). "Importantly, isoform A is the predominant form of the insulin receptor expressed in the foetus and in various types of cancer including breast, colon, lung, thyroid, prostate, and ovary." (PMID 23983688, 2013). "IGF1R/INSR hybrids have been identified in multiple human cancers." (PMID 23383308, 2013). "Expression of insulin receptor on cancer cells, which can mediate IGF signaling and maintain the malignant phenotypes, may also contribute to resistance to IGFR inhibition." (PMID 23818948, 2013). "INSR was found to be expressed on various cancer cell lines, though at different levels." (PMID 23077621, 2012). "Many studies have shown that the A isoform of insulin receptor (IR) is abnormally overexpressed in various cancer types and might promote tumor growth." (PMID 22438913, 2012). "Over-expression of both IGF-1R and INSR in cancer cells leads to an over-expression of Hybrid-R as well; however, the mechanisms that regulate Hybrid-R formation are currently unknown." (PMID 22879999, 2012). "Various chronic glomerulopathy prone conditions such as poorly controlled diabetes, malignant tumors, systemic autoimmune diseases, pregnancy are inclinable to be accompanied endocrinological/metabolic disturbance which may affect expression of InsR or IGF-1R." (PMID 23061721, 2012). "This suggests that post-transcriptional mechanisms could play a role in regulating the total protein level of insulin receptor in cancer." (PMID 22046260, 2011). "Moreover, activated INSR/IGF1R and JAK kinases in Phos3 could be associated with EMT and cancer stemness, as well as the immunosuppression." (PMID 38650175, 2024). "Interestingly, several types of cancer exhibit elevated levels of the insulin receptor." (PMID 37761999, 2023). "In particular, at this transition checkpoint, the cancer cell acquires the ability to secrete big-IGF-II and establish its autocrine stimulatory loop mediated via diversified signals that big-IGF-II exerts via the IGF-IR and the Insulin receptor fetal variant (IRA)." (PMID 38255147, 2023). "In addition, the expression levels of IGF-1R and INSR are predictive of cancer outcome." (PMID 36755926, 2023). "The question whether INSR is a druggable target in cancer is a matter of controversy." (PMID 36479090, 2022). "Proteoglycans are mainly produced by the cancer-associated fibroblasts (CAFs) in the stroma and play a role in intercellular and ECM interactions via activation of receptor tyrosine kinases (EGFR, FGFR, IGF1R, INSR) on the cancer cells regulating the proliferation and survival cascaded." (PMID 34851463, 2021). "Surprisingly, however, insulin receptor knockdown appeared to only affect immunotoxin processing and not levels of pro- or anti-apoptotic proteins as might be expected due to the role of the insulin receptor in cancer cell survival." (PMID 32630017, 2020). "These metabolic changes could affect cancer cell growth and proliferation by increasing the provision of glucose to cancer cells, and at the same time by stimulating the insulin receptor (IR)/PI3K/AKT/mTORC1 pathway and promoting tumor cell resistance to everolimus." (PMID 33182575, 2020). "The resulting autophosphorylation of the receptor recruits the insulin receptor substrate (IRS) to the membrane causing subsequent downstream activation of the PI3K/Akt/mTOR pathway and the Ras/Raf/MEK signalling pathway, which are known to be driver pathways in cancer." (PMID 27418340, 2016). "Moreover, the insulin receptor-activating signaling pathways may offer protection from invasion and metastasis of cancer cells; however, the mechanism remains unclear and requires further investigation." (PMID 25963193, 2015). "Insulin is a peptide hormone and its receptor (InsR), a tyrosine kinase, can occur in two alternatively spliced isoforms: InsR-A and InsR-B; the former is the predominant isoform in fetal life and is also the main subtype expressed in cancer as an ‘oncofetal’ phenomenon." (PMID 24493753, 2014).